CCDC43 (coiled-coil domain containing 43)
Synonyms: FLJ31795
Tractability: PROTAC: UniProt records ubiquitination sites on it; ubiquitination databases record sites on it; its protein half-life has been measured.
Gene: Protein-coding gene on chromosome 17 (44,673,069 to 44,689,779, reverse strand). Ensembl gene ENSG00000180329.
Subcellular location (Human Protein Atlas): Cytosol
Gene Ontology:
Molecular function: protein binding
Genetic constraint (gnomAD): Loss-of-function variants: 18 observed, 24.21 expected, observed/expected ratio (o/e) 0.74, 90% interval 0.51 to 1.1. The upper end of that interval is the gene's LOEUF score, 1.1, which puts it in group 4 of 6, group 1 being the genes least tolerant of losing a copy. Missense variants: 201 observed, 221.02 expected, observed/expected ratio (o/e) 0.91, 90% interval 0.81 to 1.02. Synonymous variants: 93 observed, 92.76 expected, observed/expected ratio (o/e) 1, 90% interval 0.85 to 1.19.
Homologues: Orthologues: chimpanzee CCDC43 (99% identical), macaque CCDC43 (99% identical), dog CCDC43 (96% identical), pig CCDC43 (94% identical), rat Ccdc43 (91% identical), mouse Ccdc43 (89% identical), rabbit CCDC43 (89% identical), guinea pig CCDC43 (82% identical), tropical clawed frog ccdc43 (60% identical), zebrafish ccdc43 (59% identical), Drosophila melanogaster CG9586 (34% identical).
Diseases named in the same sentence as CCDC43 in open-access papers:
CCDC43 is named in the same sentence as 12 diseases in open-access papers, as found by Europe PMC text mining. Sharing a sentence is not in itself a finding about the gene and the disease. The quoted sentences say what the papers report.
gastric cancer (10 papers, 2021 to 2025). A primary or metastatic malignant neoplasm involving the stomach. "Expression of CCDC43 has been linked to a number of aspects of gastric cancer, including tumor differentiation, distant metastasis, and clinical outcome of patients." (PMID 36061359, 2022). "In gastric cancer, CCDC43 has been shown to colocalize with four and a half LIM domain protein 1 (FHL1), but these two proteins act as antagonists." (PMID 40678420, 2025). "CCDC43 expression is predictive of poor prognosis and metastatic spread in patients with colorectal cancer, gastric cancer or oral squamous cell carcinoma (OSCC)." (PMID 37435077, 2023). "As a new member, CCDC43 could mediate the differentiation and metastasis of gastric cancer (GC), and it was closely linked with the prognosis of GC patients." (PMID 37064086, 2023). "For example, CCDC43 was proved to accelerate proliferation and metastasis process of gastric cancer." (PMID 34055889, 2021). "While CCDC43 functions as an oncogene in gastric cancer, FHL1 promotes apoptosis of GC cells." (PMID 40678420, 2025). "CCDC43 is known to play an important role in studies of gastric cancer (GC)." (PMID 40678420, 2025). "CCDC43 was found to act as a key player in several studies targeting gastric cancer." (PMID 37614502, 2023). "A recent study demonstrates that HMGA1 stimulates gastric cancer proliferation and metastasis via transactivating SUZ12 and CCDC43 expression." (PMID 38706894, 2024). "YY1 directly binds to CCDC43 and ADRM1 gene promoters, leading to their overexpression, and subsequently the aggressiveness of gastric cancer." (PMID 35747809, 2022). "Although there have been no reports showing the role of CCDC43 in cell death in the context of HCC, it was previously shown in a gastric cancer study that CCDC43 acts opposite to four and a half LIM domains 1 (FHL1), which in turn promotes cell death." (PMID 37614502, 2023).
colorectal cancer (3 papers, 2023 to 2025). A primary or metastatic malignant neoplasm that affects the colon or rectum. "CCDC43 protein has been shown to play a role in cell proliferation, invasion, metastasis, and epithelial–mesenchymal transition in gastric and colorectal cancer types." (PMID 40678420, 2025).
colon cancer (1 paper, 2022). "In previous studies, high expression of CCDC43 was found to promote metastasis of gastric and colon cancer, but so far, there is no research on CCDC43 in OSCC." (PMID 35401551, 2022).
tumor (8 papers, 2017 to 2024). "Additionally, our results showed that CCDC43 is linked to the tumor immune microenvironment of HCC and demonstrated that CCDC43 may also be a therapeutic target for checkpoint inhibitors." (PMID 37614502, 2023). "We analyzed prognostic features, tumor immune microenvironment characteristics, functional annotation and drug sensitivity prediction to explain the correlation between CCDC43 and HCC." (PMID 37614502, 2023). "The crucial involvement of CCDC43 in the tumor immune microenvironment, including T cell receptor signaling route, B cell receptor signaling pathway, apoptosis, and Th1 and Th2 cell differentiation, was further verified by GSEA analysis." (PMID 37614502, 2023). "During our study, we discovered that CCDC43 is involved in regulating several pathways related to both tumor and immune processes, including the hippo pathway." (PMID 37614502, 2023). "In patients with OSCC, high expression of CCDC43 correlates with reduced tumor infiltration by B cells, DCs, CD8+ T cells and natural killer T cells." (PMID 37435077, 2023). "In present work, we found that the levels of HMGA1 was positively related with SUZ12 or CCDC43 expression in tumor samples by Spearman’s correlation." (PMID 34167089, 2021). "In addition, the transcript levels of CCDC43 were positively correlated with Grade and Stage, suggesting that CCDC43 expression was enhanced at later stages of tumor growth and at greater extent of dissemination." (PMID 37614502, 2023). "We discover the important value of CCDC43 in clinical prognosis and tumor immunity and reveal the possible mechanism by which it mediates tumor cell interactions with other cells in TIME, which indicates that CCDC43 is expected to become an important therapeutic target for OSCC." (PMID 35401551, 2022). "Moreover, increased expression of CCDC43 is correlated with decreased anti-tumor immunity and heightened DNA damage repair capability, which could be a trigger for inducing epithelial-mesenchymal transition." (PMID 37614502, 2023). "Notably, we found higher tumor immune microenvironment with high CCDC43 expression." (PMID 37614502, 2023). "Furthermore, high expression of CCDC43 is detected in more advanced oral squamous cell carcinoma (OSCC) and results in reduced anti-tumor immunity, leading to an increased metastatic capacity of OSCC cells." (PMID 37614502, 2023). "Furthermore, CCDC43 stimulated EMT, tumor invasion and metastasis." (PMID 34167089, 2021). "The hazard ratios of LCLAT1 and CCDC43 are positive, indicating the anti- survival function of these genes, while the coefficients of other 5 genes are negative, including ENSG00000269386 (RAB11B-AS1), TOM1L2, AMPD3, MINK1 and WDTC1, indicating that they may be tumor suppressor genes." (PMID 28331188, 2017).
cancer (7 papers, 2021 to 2026). A tumor composed of atypical neoplastic, often pleomorphic cells that invade other tissues. "Therefore, the higher the expression of CCDC43, the more it promotes cell death, and there is great potential to target it in cancer therapy." (PMID 37614502, 2023). "Therefore, CCDC43 serves a vital function in cancer onset and development." (PMID 34167089, 2021). "Although CCDC43 is expressed in various tissues and cell types, previous studies have focused on its alteration in different types of cancer rather than its fundamental functions in the cell." (PMID 40678420, 2025). "CCDC43 is a member of the coiled-coil domain-containing (CCDC) family, and CCDC is considered to be involved in the proliferation, invasion, and metastasis of malignant tumor cells." (PMID 35401551, 2022). "Moreover, both HMGA1 and SUZ12/CCDC43 were highly expressed in cancer cells but not in normal gastric tissues, and their expressions were positively correlated." (PMID 34167089, 2021).
CCDC43 also shares sentences with these, for which no sentence is quoted: Oral Squamous Cell Carcinoma (2 papers); hepatocellular carcinoma (1); lung adenocarcinoma (1); Lymph Node Metastatic Tumors (1); ovarian carcinoma (1); pituitary adenoma (1); schizophrenia (1).